PPP2R1A (protein phosphatase 2 scaffold subunit Aalpha)
Diseases named in the same sentence as PPP2R1A in open-access papers (continued):
Sharing a sentence is not in itself a finding about the gene and the disease.
neurodevelopmental disorder (5 papers, 2022 to 2025). A behavioral and cognitive disorder with onset during the developmental period that involves impaired or aberrant development of intellectual, motor, or social functions. "Specifically, PP2A-related neurodevelopmental disorders are characterized by mutations in PPP2R1A (Aα), PPP2CA (Cα), PPP2R2C (B55γ), PPP2R5B (B56β), PPP2R5C (B56γ), and PPP2R5D (B56δ), with most patients and mutations, so far, found in PPP2R5D." (PMID 36313552, 2022). "This systematic review represents the most comprehensive synthesis of PPP2R1A-related neurodevelopmental disorders to date, encompassing 16 studies and 60 patients across four continents." (PMID 41465181, 2025). "Ultimately, 16 studies met the inclusion criteria and were included in the qualitative synthesis, comprising 2 cohort studies and 14 case series/reports, representing a total of 60 patients with PPP2R1A-related neurodevelopmental disorders." (PMID 41465181, 2025). "Taken together, our findings indicate that PPP2R1A-related neurodevelopmental disorders encompass a broad and heterogeneous spectrum, ranging from lethal neonatal disease to survivable forms with variable cognitive and neurological outcomes." (PMID 41465181, 2025). "Therefore, we conducted a systematic literature review of PPP2R1A-related neurodevelopmental disorders following the PRISMA guidelines to comprehensively define the clinical spectrum, characterize the mutational landscape, and explore genotype–phenotype correlations." (PMID 41465181, 2025).
adenocarcinoma (2 papers, 2023 to 2024). A common cancer characterized by the presence of malignant glandular cells. "We found that PPP2R1A was highly expressed in adenocarcinoma tissues compared with adjacent tissues." (PMID 38654331, 2024).
infection (2 papers, 2023 to 2025). The state of being infected such as from the introduction of a foreign agent such as serum, vaccine, antigenic substance or organism. "Besides, we also detected viral genes transcriptional levels after inhibiting PPP2R1A expression with siRNAs in KSHV de novo infection." (PMID 41337097, 2025). "Taken together, we demonstrated that PPP2R1A can promote RTA dephosphorylation in both KSHV de novo infection and lytic replication, broadened our understanding of RTA phosphorylation and underscored the complicated and diversity of the interaction between RTA and PPP2R1A in KSHV lifecycle." (PMID 41337097, 2025). "We firstly constructed a cell line that stably expressed Flag-tagged PPP2R1A in SLK cells, named SLK-PPP2R1A, and utilized the recombinant rKSHV.219 to perform KSHV de novo infection experiments." (PMID 41337097, 2025). "Therefore, we further explored the function and biological significance of interaction between PPP2R1A and RTA in KSHV de novo infection." (PMID 41337097, 2025).
PPP2R1A also shares sentences with these, for which no sentence is quoted: epilepsy (4 papers); leukemia (3); Cognitive impairment (2); ovarian serous adenocarcinoma (2); acute leukemia (1); amyotrophic lateral sclerosis (1); astrocytoma (1); Autoimmunity (1); B-cell acute lymphoblastic leukemia (1); breast invasive carcinoma (1); colorectal adenocarcinoma (1); congenital hydrocephalus (1); COVID-19 (1); endometrial tumors (1); escherichia coli infection (1); head and neck squamous cell carcinoma (1); heart failure (1); Houge-Janssens syndrome 2 (1); Hydrocephalus (1); infantile spasms (1); intestinal tumours (1); Macrocephaly (1); malignant mesothelioma (1); mucinous carcinoma (1); myocarditis (1); neurodegenerative disease (1); neurological diseases (1); Obesity (1); obstructive sleep apnea (1); oligodendroglioma (1).
A further 10 diseases each share a sentence with PPP2R1A in 1 paper.